IGKV2-40 (immunoglobulin kappa variable 2-40)
Description:
V region of the variable domain of immunoglobulin light chains that participates in the antigen recognition. Immunoglobulins, also known as antibodies, are membrane-bound or secreted glycoproteins produced by B lymphocytes. In the recognition phase of humoral immunity, the membrane-bound immunoglobulins serve as receptors which, upon binding of a specific antigen, trigger the clonal expansion and differentiation of B lymphocytes into immunoglobulins-secreting plasma cells. Secreted immunoglobulins mediate the effector phase of humoral immunity, which results in the elimination of bound antigens. The antigen binding site is formed by the variable domain of one heavy chain, together with that of its associated light chain. Thus, each immunoglobulin has two antigen binding sites with remarkable affinity for a particular antigen. The variable domains are assembled by a process called V-(D)-J rearrangement and can then be subjected to somatic hypermutations which, after exposure to antigen and selection, allow affinity maturation for a particular antigen.
Synonyms: IGKV240; O11; O11a
Gene: Immunoglobulin variable (V) gene on chromosome 2 (89,330,116 to 89,330,429, reverse strand). Ensembl gene ENSG00000273962.
Subcellular location: Secreted; Cell membrane
Gene Ontology:
Biological process: immune response
Cellular component: extracellular region; immunoglobulin complex; plasma membrane
Homologues: Orthologues: mouse Igkv2-109 (75% identical). Paralogues in human: IGKV2D-40 (99% identical), IGKV2-28 (86% identical), IGKV2D-28 (86% identical), IGKV2D-29 (84% identical), IGKV2-24 (79% identical), IGKV2-30 (78% identical), IGKV2D-24 (77% identical), IGKV2D-30 (77% identical), IGKV2D-26 (74% identical), IGKV4-1 (61% identical), IGKV3-20 (58% identical), IGKV3-11 (56% identical), and 81 more.